MTRR (5-methyltetrahydrofolate-homocysteine methyltransferase reductase)
Description:
Key enzyme in methionine and folate homeostasis responsible for the reactivation of methionine synthase (MTR/MS) activity by catalyzing the reductive methylation of MTR-bound cob(II)alamin. Cobalamin (vitamin B12) forms a complex with MTR to serve as an intermediary in methyl transfer reactions that cycles between MTR-bound methylcob(III)alamin and MTR bound-cob(I)alamin forms, and occasional oxidative escape of the cob(I)alamin intermediate during the catalytic cycle leads to the inactive cob(II)alamin species (Probable). The processing of cobalamin in the cytosol occurs in a multiprotein complex composed of at least MMACHC, MMADHC, MTRR and MTR which may contribute to shuttle safely and efficiently cobalamin towards MTR in order to produce methionine. Also necessary for the utilization of methyl groups from the folate cycle, thereby affecting transgenerational epigenetic inheritance (By similarity). Also acts as a molecular chaperone for methionine synthase by stabilizing apoMTR and incorporating methylcob(III)alamin into apoMTR to form the holoenzyme. Also serves as an aquacob(III)alamin reductase by reducing aquacob(III)alamin to cob(II)alamin; this reduction leads to stimulation of the conversion of apoMTR and aquacob(III)alamin to MTR holoenzyme.
Synonyms: MSR; cblE
Tractability: Small molecule: a structure with a bound ligand is known. PROTAC: ubiquitination databases record sites on it.
Safety:
Unwanted effects reported when the protein is acted on. In parentheses: how it was acted on, where the effect was seen, and who reports it.
drug toxicity (source: ClinPGx)
Gene: Protein-coding gene on chromosome 5 (7,851,186 to 7,906,025, forward strand). Ensembl gene ENSG00000124275.
Subcellular location: Cytoplasm (Isoform B); Cytoplasm (Isoform A)
Subcellular location (Human Protein Atlas): Cytosol; Nucleoplasm; Intermediate filaments
Pathways (Reactome):
Metabolism: Cobalamin (Cbl) metabolism; Methylation; Sulfur amino acid metabolism
Disease: Defective MTR causes HMAG; Defective MTRR causes HMAE
Gene Ontology:
Molecular function: [methionine synthase] reductase (NADPH) activity; FAD binding; flavin adenine dinucleotide binding; FMN binding; molecular carrier activity; NADPH binding; NADPH-hemoprotein reductase activity; oxidoreductase activity, acting on metal ions, NAD or NADP as acceptor; protein binding; oxidoreductase activity
Biological process: folic acid metabolic process; homocysteine catabolic process; L-methionine biosynthetic process; cobalamin metabolic process; homocysteine metabolic process; S-adenosylmethionine cycle; L-amino acid metabolic process
Cellular component: cytosol; cytoplasm
Genetic constraint (gnomAD): Loss-of-function variants: 60 observed, 79.81 expected, observed/expected ratio (o/e) 0.75, 90% interval 0.61 to 0.93. The upper end of that interval is the gene's LOEUF score, 0.93, which puts it in group 3 of 6, group 1 being the genes least tolerant of losing a copy. Missense variants: 889 observed, 880.17 expected, observed/expected ratio (o/e) 1.01, 90% interval 0.95 to 1.07. Synonymous variants: 355 observed, 330.99 expected, observed/expected ratio (o/e) 1.07, 90% interval 0.98 to 1.17.
Gene-disease validity (ClinGen):
ClinGen rates the evidence that MTRR causes each of these diseases.
methylcobalamin deficiency type cblE (autosomal recessive): Definitive.
Homologues: Orthologues: chimpanzee MTRR (98% identical), macaque MTRR (95% identical), dog MTRR (84% identical), rabbit MTRR (81% identical), pig MTRR (80% identical), rat Mtrr (79% identical), mouse Mtrr (79% identical), guinea pig MTRR (76% identical), tropical clawed frog mtrr (56% identical), zebrafish mtrr (54% identical), Caenorhabditis elegans mtrr-1 (31% identical), Drosophila melanogaster CG14882 (20% identical). Paralogues in human: POR (29% identical), NOS3 (27% identical), NOS2 (27% identical), NDOR1 (26% identical), NOS1 (25% identical).
Diseases named in the same sentence as MTRR in open-access papers:
MTRR is named in the same sentence as 98 diseases in open-access papers, as found by Europe PMC text mining. Sharing a sentence is not in itself a finding about the gene and the disease. The quoted sentences say what the papers report.
hyperhomocysteinemia (10 papers, 2012 to 2024). A serious metabolic condition caused by mutations in the MTHFR gene, medications, or nutritional deficiency. "Polymorphic AG and GG variants for MTRR rs1801394 are associated with changes in the methionine synthase reductase conformation and a decrease in its activity, leading to impaired folate metabolism, hyperhomocysteinemia and atherosclerosis." (PMID 35207533, 2022). "The Mtrrgt allele in mice is robust enough to cause many of the same phenotypes as humans with MTRR mutations or folate deficiency (e.g., hyperhomocysteinemia, anaemia, neural tube defects, fetal growth restriction) [21,30,]." (PMID 32257815, 2020). "Methylenetetrahydrofolate reductase (MTHFR) (C677T and A1298C) and methionine synthase reductase (MTRR) mutations (A66G) cause mild hyperhomocysteinemia and low folate level and are associated with several disorders." (PMID 27089387, 2016). "MTRR g.66A>G polymorphism has been associated with reduced activity of MTRR enzyme resulting in hyperhomocysteinemia and altering the methylation of DNA." (PMID 22175024, 2012). "Deficiency of these cofactors and mutation in methylenetetrahydrofolate reductase (MTHFR) and methionine synthase reductase (MTRR) could lead to excessive accumulation of plasma Hcy called hyperhomocysteinemia (HHcy)." (PMID 37183324, 2023). "MTRR plays an important role in the remethylation of homocysteinemia (Hcy) to methionine." (PMID 34917626, 2021). "MTRR is involved in the homocysteine and folate metabolic pathway via its activation of methionine synthase via reductive methylation and is consequently a critical determinant of homocysteinemia levels." (PMID 27089387, 2016). "The hyperhomocysteinemia occurrence may be related to both vitamin deficiency and genetic abnormalities of methyltetrahydrofolate reductase (MTHFR) and methionine synthase reductase (MTRR) enzymes." (PMID 26487487, 2015). "The 5–10-methylenetetrahydrofolate reductase (MTHFR) C677T and A1298C and methionine synthase reductase (MTRR) A66G gene, may contribute to the risk of the development of hyperhomocysteinemia and are now believed to be good candidate for susceptibility to dyslipidemia and insulin resistance." (PMID 31200713, 2019). "Mutations in some key genes encoding homocysteine-metabolizing enzymes, such as methylenetetrahydrofolate reductase (MTHFR) C677T and A1298C and methionine synthase reductase (MTRR) A66G, may contribute to the risk of the development of hyperhomocysteinemia and thus leas to clinical disorders." (PMID 27089387, 2016).
breast carcinoma (7 papers, 2014 to 2025). "In some case-control studies, certain polymorphisms in fibroblast growth factor receptor 2 (FGFR2) and methionine synthase reductase (MTRR) were indicated to elevate individual susceptibility in postmenopausal breast cancer." (PMID 25531440, 2014). "Variation in folate-pathway genes such as MTHFR, MTR and MTRR may disrupt homeostasis and confer significant risk of breast cancer, attributable to impaired DNA repair." (PMID 28241424, 2017). "This study aimed to examine the joint effects of folate intake, polymorphisms of 5,10- methylenetetrahydrofolate reductase (MTHFR), methionine synthesis reductase (MTRR) and methionine synthase (MTR) genes and breast cancer risk." (PMID 27404801, 2016). "Therefore, we investigated whether the genetic variants of the SHMT, MS, MTRR and CBS gene can affect plasma Hcy levels and are associated with breast cancer risk." (PMID 24559276, 2014).
homocystinuria (7 papers, 2015 to 2024). An autosomal recessive inherited metabolic disorder caused by mutations in the CBS, MTHFR, MTR, and MTRR genes. "Mutations in MMAA, MMAB, and MUT (corresponding to cblA, cblB, and mut complementation groups) are associated with isolated methylmalonic aciduria, while mutations in MTRR and MTR (corresponding to cblE and cblG complementation groups) are associated with isolated homocystinuria." (PMID 38203763, 2024). "Genetic polymorphisms of MTHFR, MTR, MTRR, MMAA (methylmalonic aciduria (cobalamin deficiency) cb1A type), MMACHC (methylmalonic aciduria and homocystinuria, cblC type), and MUT have been analyzed." (PMID 32564308, 2020). "We have recently reported that the most frequent mutation in the methionine synthase reductase (MTRR) gene, a deep intronic mutation (c.903+469T>C), creates an SRSF1 binding ESE, which leads to pseudoexon inclusion and causes the cblE type of homocystinuria." (PMID 25878036, 2015).
spina bifida (7 papers, 2007 to 2025). A congenital neural tube defect in which vertebrae are not fully formed. "In relation to neurological conditions, some studies have been reported that MTRR gene 66GG was associated with spina bifida, Down syndrome, and intellectual disability." (PMID 39071225, 2024). "MTRR gene polymorphisms (particularly rs1801394) have been investigated as a risk factor for both spina bifida and congenital heart defects." (PMID 19493349, 2009). "As in the exome dataset of proband SB1A with the EFNB1 variant (rs772228172), four variants were annotated as homozygous (CUBN, COMT, PTCH1 and TRDMT1) and eight variants as heterozygous (CUBN,MTRR, and VANGL1) in the reported spina bifida-related genes." (PMID 35741713, 2022). "Other report demonstrated that rs9332 in MTRR had connections with spina bifida and conotruncal heart defects." (PMID 24278388, 2013). "Genetic factors including variations in some specific genes such as MTHFR, MTHFD1, MTRR, VANGL1, VANGL2, CELSR1, and FUZ, as well as variants in the T-locus on chromosome 6q have also been studied in the development of spina bifida and other spinal dysmorphisms." (PMID 39835283, 2025).
folate deficiency (6 papers, 2015 to 2024). A nutritional condition produced by a deficiency of FOLIC ACID in the diet. "We have developed a mouse model with a hypomorphic mutation in the Mtrr gene (Mtrrgt) that displays many key features of dietary folate deficiency or MTRR mutations in humans." (PMID 32257815, 2020). "We aimed to explore the joint effect of the methylenetetrahydrofolate reductase (MTHFR) C677T and A1298C, methionine synthase (MTR) A2756G, and methionine synthase reductase (MTRR) A66G polymorphisms on folate deficiency in a Chinese hypertensive population." (PMID 26266420, 2015). "Furthermore, we have demonstrated that not only pairwise gene-gene interactions but also higher-order interactions of these gene polymorphisms (MTHFR C677T, MTHFR A1298C, MTR A2756G, and MTRR A66G) more strongly influence the incidence of folate deficiency." (PMID 26266420, 2015). "Common polymorphisms of MTHFR (C677T and A1298C), MTRR (A66G) and MTR (A2756G) enzymes may influence the serum folate level and contribute to folate deficiency." (PMID 36554014, 2022). "Folic acid deficiency, MTHFD1 rs2236225, MTHFR rs1801133, MTRR rs1801349 and RFC1 rs1051226 polymorphisms may be maternal risk factors of NTDs." (PMID 30867013, 2019).
Obesity (5 papers, 2015 to 2021). Accumulation of substantial excess body fat. "Little is known regarding the interactions of methylenetetrahydrofolate reductase (MTHFR) C677T and methionine synthase reductase (MTRR) A66G polymorphisms with overweight/obesity on serum lipid profiles." (PMID 27793164, 2016). "Several studies have examined the associations of methylenetetrahydrofolate reductase (MTHFR) C677T and methionine synthase reductase (MTRR) A66G polymorphisms with being overweight/obesity." (PMID 26016497, 2015). "Furthermore, the C677T polymorphism in the MTHFR gene and the A66G polymorphism in the MTRR (methionine synthase reductase) gene were evaluated as potential candidates responsible for an increased risk of obesity." (PMID 31344895, 2019). "Although both methylenetetrahydrofolate reductase (MTHFR) C677T and methionine synthase reductase (MTRR) A66G polymorphisms have been associated with type 2 diabetes (T2D), their interactions with being overweight/obesity on T2D risk remain unclear." (PMID 27983710, 2016).
autism (4 papers, 2016 to 2024). Persistent deficits in social interaction and communication and interaction as well as a markedly restricted repertoire of activity and interest as well as repetitive patterns of behavior. "Genetic variant distribution in ASD cases: While six autism cases had a heterozygous (AG) genotype in the MTRR gene (rs1801394), one case had a homozygous (GG) genotype in the MTRR gene." (PMID 38807972, 2024). "Three autism patients are heterozygous in the Transcobalamin (TCN1) (rs526934-G) gene, six are heterozygous in the methionine synthase reductase (MTRR) (rs1801394-G) gene, and one is homozygous (GG) in the MTRR gene." (PMID 38807972, 2024). "In our study, three of the autism patients were heterozygous (AG) in the TCN1 (rs526934) gene, six were heterozygous (AG) in the MTRR (rs1801394) gene, and one was a homozygous (GG) genotype in the MTRR gene." (PMID 38807972, 2024).
gonococcal infection (4 papers, 2021 to 2024). "The types of mtrR alleles were determined for the first time in the Russian population of the causative agent of gonorrhea." (PMID 36671371, 2023). "As mentioned, MtrR also represses directly the expression of rpoH, which encodes an oxidative stress response sigma factor that is critical in the defense against reactive oxygen species (ROS) present at gonococcal infection sites." (PMID 38326294, 2024). "The AMR determinants that conferred elevated MICs of azithromycin, including 23S rRNA and mtrR, were examined because azithromycin is part of dual therapy for the treatment of gonorrhea." (PMID 35905043, 2022). "In our previous work, we identified residue W136, which is located on α7, as a critical residue for induction of MtrR by chenodeoxycholate, a bile salt present at extra-genital gonococcal infection sites." (PMID 33784401, 2021). "However, physiologically relevant inducers of MtrR that are found at urogenital sites, which form the vast majority of the sites of gonococcal infection, are not known, posing a significant gap in our understanding of how MtrR contributes to MDR and gonococcal survival in the reproductive tract." (PMID 38326294, 2024).
ischemic stroke (4 papers, 2011 to 2026). A stroke disorder caused by obstruction of blood flow to the brain, due to thrombotic (local blood clot formation) or embolic (due to a blood clot or other material traveling from another site) event. "In this study, we evaluated the association between the genetic polymorphisms of methylenetetrahydrofolate reductase (MTHFR), methionine synthesis reductase (MTR), and methyltransferase reductase (MTRR) genes and ischemic stroke risk in Chinese population." (PMID 30884202, 2019). "Our study suggested that deficiency of both folate and vitamin B12 levels, caused by a combination of genetic variations at SHMT1, MTRR and TCN2, may jointly increase ischemic stroke risk." (PMID 21935458, 2011). "Experimental and clinical data suggest that cytokine dysregulation and polymorphisms of thrombophilia-related genes (MTHFR, MTR, and MTRR) may jointly promote hypercoagulation, endothelial dysfunction, and thromboinflammation, thereby contributing to post-COVID ischemic stroke." (PMID 41898515, 2026). "SNP analysis from the initial study suggested 3 risk variants in the MTRR, SHMT1 and TCN2 genes which were moderately associated with ischemic stroke risk, independent of known stroke risk factors." (PMID 21935458, 2011).
lung carcinoma (4 papers, 2007 to 2019). "In this study, we aimed to evaluate the association of serum folate concentration and of six known functional variations in MTHFR, MTR, MTRR genes and the risk of lung cancer in Poland." (PMID 28493936, 2017). "CBS (rs2850146) and MTRR (rs3776467) SNPs may, in combination with high folic acid levels, protect against lung cancer." (PMID 25988111, 2014). "The analysis of variations in MTHFR, MTR and MTRR genes did not reveal any significant difference between lung cancer cases and controls in univariable and multivariable analyses." (PMID 28493936, 2017). "The distribution of the genotypes in six tested SNPs in MTHFR (rs1801131, rs1801133), MTR (rs1805087) and MTRR (rs1801394, rs1532268, rs10380) genes was not significantly different between lung cancer patients and healthy controls." (PMID 28493936, 2017).
migraine (4 papers, 2013 to 2016). "Similarly, the A allele carriers of the methionine synthase reductase (MTRR A66G) variants also showed significantly greater reductions in homocysteine levels, the severity of pain in migraine, and the percentage of migraine disability when compared with those with the GG genotypes." (PMID 25815319, 2015). "Therefore, a recent pharmacogenetic study evaluated the effects of different MTHFR and 5-methyltetrahydrofolate-homocysteine methyltransferase reductase (MTRR) genotypes on the occurrence of migraine in a double-blinded placebo-controlled trial of daily vitamin B supplementation." (PMID 23848401, 2013). "Similarly while the previous trial reported migraine associated variants, in the MTHFR and MTRR genes to have a significant effect on migraine treatment response, the current trial did not observe any significant effect of the MTHFR C677T gene variant on migraine treatment response." (PMID 27339806, 2016).
thrombophilia (4 papers, 2024 to 2026). A condition characterized by an abnormally high level of thrombi. "The most prevalent hereditary types of thrombophilia associated with preeclampsia are factor V Leiden mutation and genetic polymorphism of folate metabolism pathway-related genes (methionine synthase reductase (MTRR) and methylenetetrahydrofolate reductase (MTHFR) enzymes)." (PMID 39336076, 2024). "This study found that genotypes of seven thrombophilia genes, including MTHFR, SERPINE1, MTR, ANXA5, MTRR PROZ, and VEGFA, are associated with inherited thrombophilia risk for RPL-RIF." (PMID 39498089, 2024).
vitamin B12 deficiency (4 papers, 2020 to 2024). A disease characterized by low serum levels of vitamin B12, either inherited or acquired. "MTRR impacts methionine synthase, leading to vitamin B12 deficiency." (PMID 40822568, 2024).
congenital heart disease (3 papers, 2018 to 2025). A heart disease that is present at birth. "Variants in the MTR and MTRR genes associated with congenital heart disease in humans." (PMID 39062651, 2024).
Hypertension (3 papers, 2012 to 2024). The presence of chronic increased pressure in the systemic arterial system. "Polymorphisms of the MTHFR gene are strongly associated with hypertension, and Met synthase 2756A > G and 5-methyltetrahydrofolate-homocysteine methyltransferase reductase 66A > G polymorphisms related to folate metabolism may serve as genetic markers for hypertension risk." (PMID 36352848, 2022).
neural tube defect (3 papers, 2009 to 2025). A congenital defect characterized by failure of the neural tube to close completely; this results in the presence of openings in the brain or spinal cord. "variations in these genes, particularly MTHFR c.677C>T and MTRR c.66A>G, have been implicated in multiple disorders, including neural tube defects, cardiovascular diseases, malignancies, and neurodevelopmental anomalies." (PMID 41362561, 2025). "MTRR gene has been shown to be associated with Homocystinuria-Megaloblastic Anemia, Cble Complementation Type and Neural Tube Defects, Folate-Sensitive." (PMID 35911393, 2022). "Disturbances in the catalytic activity of MTRR could lead to higher levels of Hcy, and this can be a risk factor for neural tube defects (NTD)." (PMID 19657388, 2009).